ASPN (asporin)
Description:
Negatively regulates periodontal ligament (PDL) differentiation and mineralization to ensure that the PDL is not ossified and to maintain homeostasis of the tooth-supporting system. Inhibits BMP2-induced cytodifferentiation of PDL cells by preventing its binding to BMPR1B/BMP type-1B receptor, resulting in inhibition of BMP-dependent activation of SMAD proteins (By similarity). Critical regulator of TGF-beta in articular cartilage and plays an essential role in cartilage homeostasis and osteoarthritis (OA) pathogenesis. Negatively regulates chondrogenesis in the articular cartilage by blocking the TGF-beta/receptor interaction on the cell surface and inhibiting the canonical TGF-beta/Smad signal. Binds calcium and plays a role in osteoblast-driven collagen biomineralization activity.
Synonyms: PLAP-1; PLAP1; SLRR1C; FLJ20129; OS3
Tractability: Antibody: UniProt places it where antibodies can reach, with high confidence; its Gene Ontology location is reachable by antibodies, with high confidence; UniProt predicts a signal peptide or a membrane-spanning region.
Gene: Protein-coding gene on chromosome 9 (92,456,205 to 92,492,208, reverse strand). Ensembl gene ENSG00000106819.
Subcellular location: Secreted, extracellular space, extracellular matrix
Subcellular location (Human Protein Atlas): Nucleoplasm; Cytosol; Predicted to be secreted
Pathways (Reactome):
Extracellular matrix organization: ECM proteoglycans
Gene Ontology:
Molecular function: calcium ion binding; extracellular matrix structural constituent conferring compression resistance
Biological process: bone mineralization; negative regulation of transforming growth factor beta receptor signaling pathway; negative regulation of tooth mineralization; response to fluoride
Cellular component: extracellular matrix; gel phase of interstitial matrix
Genetic constraint (gnomAD): Loss-of-function variants: 23 observed, 21.33 expected, observed/expected ratio (o/e) 1.08, 90% interval 0.77 to 1.53. The upper end of that interval is the gene's LOEUF score, 1.53, which puts it in group 6 of 6, group 1 being the genes least tolerant of losing a copy. Missense variants: 299 observed, 365.61 expected, observed/expected ratio (o/e) 0.82, 90% interval 0.74 to 0.9. Synonymous variants: 115 observed, 134.19 expected, observed/expected ratio (o/e) 0.86, 90% interval 0.74 to 1.
Homologues: Orthologues: chimpanzee ASPN (99% identical), macaque ASPN (96% identical), mouse Aspn (89% identical), pig ASPN (89% identical), rat Aspn (89% identical), guinea pig ASPN (87% identical), rabbit ASPN (87% identical), dog ASPN (86% identical), tropical clawed frog aspn (73% identical), zebrafish aspn (54% identical). Paralogues in human: BGN (53% identical), DCN (48% identical), PODN (26% identical), LRRC4 (24% identical), FLRT1 (22% identical), LRRC4B (22% identical), LRRC4C (22% identical), PODNL1 (22% identical), LRRTM4 (22% identical), FLRT3 (21% identical), FLRT2 (21% identical), LRRTM3 (21% identical), and 10 more.
Diseases named in the same sentence as ASPN in open-access papers:
ASPN is named in the same sentence as 90 diseases in open-access papers, as found by Europe PMC text mining. Sharing a sentence is not in itself a finding about the gene and the disease. The quoted sentences say what the papers report.
osteoarthritis (23 papers, 2006 to 2025). A noninflammatory degenerative joint disease occurring chiefly in older persons, characterized by degeneration of the articular cartilage, hypertrophy of bone at the margins and changes in the synovial membrane. "Asporin (ASPN) is a secreted matrix protein associated with cancer, osteoarthritis and periodontal membrane mineralization." (PMID 36254001, 2022). "As well as asporin other genes which belong to TGF-β signaling pathway are associated with osteoarthritis, including GFD5 and SMAD3." (PMID 29233086, 2017). "The D14 allele of ASPN was over-represented in osteoarthritis subjects, and D14 allele showed greater inhibition of TGF-β1 activity than the common allele, D13." (PMID 21329514, 2011). "A functional aspartic acid (D) repeat polymorphism of ASPN was first described as an osteoarthritis-associated polymorphism." (PMID 21329514, 2011). "Recently, an aspartic acid repeat polymorphism of ASPN was first described as an osteoarthritis-associated polymorphism." (PMID 21329514, 2011). "There are now three polymorphisms thought to be strongly associated with osteoarthritis (OA) susceptibility; these occur in the asporin gene (ASPN), the secreted frizzled-related protein 3 gene (FRZB), and the calmodulin 1 gene (CALM1)." (PMID 19327154, 2009). "Recent studies have identified populations of individuals with osteoarthritis of the knee and asporin alleles with 14 aspartic acid repeats in the N-terminal region of the protein (designated D14)." (PMID 19327154, 2009). "A recent genetic association study has identified a microsatellite in the coding sequence of the asporin gene as a susceptibility factor for osteoarthritis (OA)." (PMID 16542493, 2006). "Thus, although asporin shows significant associations with osteoarthritis, functional differences among D-repeat polymorphisms in asporin are still unclear." (PMID 31608236, 2019). "Therefore, the relationship between asporin polymorphisms and osteoarthritis still needs to be investigated in large-scale studies of different ethnic populations." (PMID 31608236, 2019). "In addition to being involved in the pathogenesis of osteoarthritis, asporin has been reported to be associated with disc degeneration." (PMID 28646230, 2017). "An allelic variant of ASPN has been implicated in osteoarthritis and lumbar disc degeneration." (PMID 21693067, 2011). "Two studies have demonstrated that asporin D14 variants increase susceptibility to and severity of knee osteoarthritis in Japanese and Chinese Han populations, whereas D13 was found to be significantly protective against osteoarthritis in some Japanese populations." (PMID 31608236, 2019). "Genes associated with DDH and osteoarthritis include FRZB, CX3CR1, ASPN, DKK1, PDRG1, GDF5, UQCC1, and TGF-β1." (PMID 41019141, 2025). "The current study presented that overexpression of miR-26b-5p contributes to preventing chondrocyte senescence and osteoarthritis (OA) by targeting asporin mRNA." (PMID 38632250, 2024). "ASPN has been reported to be involved in the pathophysiological processes of various diseases, including cancer, osteoarthritis, and intervertebral disc disease." (PMID 36011263, 2022). "ASPN is significantly up-regulated in osteoarthritis, and miR-4303 targets negative regulation of ASPN expression to alleviate inflammation in chondrocytes." (PMID 36011263, 2022). "Our findings showed that ASPN was significantly up-regulated in osteoarthritis, indicating that ASPN played a positive role in osteoarthritis progression." (PMID 34663368, 2021). "In summary, ASPN alleviated osteoarthritis by regulating chondrocyte bioactivity and the release of inflammatory factors from chondrocytes." (PMID 34663368, 2021). "Because of the unique D repeat sequence of aspartic acid residue at the N terminal of ASPN, it is considered a vital protein secreted by chondrocytes and participates in regulating osteoarthritis pathogenesis." (PMID 34663368, 2021).
osteoarthritis (continued). "In this study, we reported two SNPs of osteoarthritis-related genes, rs7775 in the FRZB gene and rs7033979 in the ASPN gene, showed significant associations with KBD in Tibetans." (PMID 28651521, 2017). "ASPN is considered a biological marker for osteoarthritis development in humans and mice." (PMID 36003650, 2022). "What is more, ASPN regulates various cytokines to relieve osteoarthritis, such as TGF-β." (PMID 34663368, 2021). "Asporin, a class I small leucine-rich proteoglycan, regulates chondrogenesis, and inhibits TGFβ1-induced expression of matrix genes, acting as a critical regulator of joint diseases, including osteoarthritis." (PMID 32656202, 2020). "A downregulated gene, Aspn (asporin) encodes a class I small leucine-rich proteoglycan (SLRP) that is expressed in very low levels in the EGP and was shown to be responsive to different cytokines in human articular chondrocytes and involved in osteoarthritis." (PMID 28718808, 2017). "Moreover, unlike other proteoglycans, asporin contains an aspartic acid repeat in its N-terminal region, polymorphisms of which have been associated with osteoarthritis." (PMID 26327350, 2015). "Asporin (ASPN) plays an important role in the regulation of cartilage development and osteoarthritis (OA) pathology." (PMID 36809926, 2023). "There is an additional regulatory feedback loop between asporin and BMP-2, which is also correlated with the severity of osteoarthritis." (PMID 31608236, 2019). "Unlike the other class I SLRPs (decorin and biglycan), asporin contains a unique and conserved stretch of aspartate (D) residues in its N terminus, and germline polymorphisms in the D-repeat-length are associated with osteoarthritis and prostate cancer progression." (PMID 31608236, 2019). "Recently, an extracellular matrix protein, asporin (ASPN), was shown to be upregulated in articular cartilage during osteoarthritis, a progressive degenerative joint disease." (PMID 28646230, 2017). "ASPN secreted by chondrocytes binds to type I collagen through its LRR domain, affects collagen fiber production, and is involved in regulating the pathogenesis of osteoarthritis." (PMID 36011263, 2022). "Therefore, asporin and TGF-β1 form a functional feedback loop in cartilage and play vital roles in homeostasis and the pathogenesis of osteoarthritis." (PMID 31608236, 2019). "We were intrigued by the low expression of asporin in normal human tissues, its high expression in breast carcinoma, and, particularly, its previously reported interaction with TGF-β1 in the context of osteoarthritis." (PMID 26327350, 2015).
gastric cancer (19 papers, 2010 to 2025). A primary or metastatic malignant neoplasm involving the stomach. "Another member of the class I SLRP, asporin, has been identified as a potential diagnostic marker at the gene level for colorectal and gastric cancers." (PMID 36765749, 2023). "Scirrhous gastric cancer cells stimulate CAFs to express ASPN, which in turn causes increased invasion of both cell types in vitro and in vivo." (PMID 36358747, 2022). "Additionally, expression of ASPN, which encodes an extracellular substrate in gastric cancer, and other inflammatory response genes (Mmp‐1, Mmp‐3) was increased in both CEFs and CAFs (green box)." (PMID 34379869, 2022). "In gastric cancer, asporin, which is upregulated at various stages of gastric cancer, has been suggested to suppress the cancer cell apoptosis and promote cell proliferation by activating LEF1‐mediated gene transcription independently of β‐catenin." (PMID 39887653, 2025). "In gastric cancer, ASPN suppresses apoptosis in gastric cancer cells by regulating β-catenin-independent LEF1-mediated gene transcription." (PMID 40810004, 2025). "Asporin has been shown to strongly inhibit apoptosis, promote growth in gastric cancer cells, and selectively promote LEF1 binding to activate the promoters of PTGS2, IL-6, and WISP1 to facilitate their transcription." (PMID 39296492, 2024). "In scirrhous gastric cancer, asporin is predominantly secreted by CAFs and this leads to the activation of Rac1 through interaction with CD44." (PMID 36765749, 2023). "For example, ASPN was reported to enhance tumor invasion and cancer-associated fibroblasts via activation of the CD44-Rac1 pathway in gastric cancer." (PMID 36386304, 2022). "Eight out of 38 upregulated genes in gastric cancer (ASPN, COL1A1, COL1A2, COL3A1, COL5A1, FAP, FN1, and SPARC) overlapped with the CAF markers list (circos plot on the left)." (PMID 35739492, 2022). "In conclusion, the present study is the first to investigate roles of asporin, decorin and their interaction with TGFβ in gastric cancer tissue and corresponding normal tissues." (PMID 34379688, 2021). "ASPN mRNA expression and prognosis of patients with gastric carcinoma was analysed based on TCGA and GEO datasets." (PMID 34379688, 2021). "ASPN was suggested to be an oncoprotein in most cancer types, such as prostate cancer, pancreas cancer, and scirrhous gastric cancers, while tumor suppressive effects of ASPN were also described in triple-negative breast cancer." (PMID 30728352, 2019). "Analysis of other cancer types showed significantly worse overall survival of ovarian and gastric cancer with high asporin expression." (PMID 27409832, 2016). "Asporin has also been reported to be expressed by gastric cancer cell lines and to enhance their oncogenic properties." (PMID 27409832, 2016). "Asporin has been reported as a tumor suppressor in breast cancer, while asporin-activated invasion has been described in gastric cancer." (PMID 27409832, 2016). "ASPN is an extracellularly secreted protein that is reported to be predominantly expressed in stromal CAFs in malignant pathogenesis of human pancreatic, colorectal and gastric cancers." (PMID 39342193, 2024). "On the other hand, ASPN is increased in gastric cancer and can also interact with TGFβ." (PMID 36358747, 2022). "Experimental evidence shows that the gastric cancer cell line 44As3 promotes asporin expression in CAFs via a mechanism in which, asporin as a unique class I SLRP, enhances the co-invasion of CAFs and cancer cells both in vitro and in vivo through the CD44/Rac1 mediated axis." (PMID 31608236, 2019). "Thus far, in tumor, high expression of asporin protein has been confirmed in pancreas, breast, prostate, and, recently, scirrhous gastric cancers." (PMID 26327350, 2015). "However, recent data on asporin overexpression in gastric cancer show an opposite, pro-invasive function for this stromal protein." (PMID 26327350, 2015).
gastric cancer (continued). "Because ASPN is predominantly expressed in tumor fibroblasts, but rarely expressed in gastric cancer cells (around 10%), and soluble ASPN upregulated unique pathways in NFs, ASPN may be important as an educational factor, and the genes upregulated by soluble ASPN could represent the CEF phenotype." (PMID 34379869, 2022). "ASPN is thought to activate the SMAD2 pathway to induce EMT, as higher levels of phosphorylated SMAD2 have been observed in gastric cancer tissue compared with adjacent normal tissue." (PMID 36358747, 2022). "We previously identified asporin (ASPN), a small leucine‐rich proteoglycan, as the major extracellular matrix protein secreted by CAFs in gastric cancer." (PMID 34379869, 2022). "ASPN, an extracellular matrix protein, which inhibits TGF-β and BMP2, is overexpressed in the gastric cancers relative to the paired normal." (PMID 21092330, 2010). "Asporin (ASPN), a small proteoglycan, mitigates oxidative stress in gastric cancer cells and activates the Rac1 signaling pathway through the upregulation of cluster of differentiation 44 (CD44), thereby enhancing the migratory and invasive capabilities of these cells." (PMID 41188920, 2025). "In gastric cancer, ASPN‐positive CAF‐like cells did not largely overlap with α‐SMA+ CAFs, suggesting that ASPN+ fibroblasts have distinct functions in the TME." (PMID 34379869, 2022). "To confirm ASPN‐mediated upregulation of the KYN pathway in other cells, and to confirm that its cytocidal effect on CD8+ T cells depends on KYN pathway metabolites, we used a gastric cancer cell line, HSC‐43, which is more stable than NF cells after gene overexpression." (PMID 34379869, 2022). "Therefore, from a molecular perspective, the asporin/CD44/EMT signaling pathway could be considered as a potential therapeutic target axis to decrease tumor migration and invasion in pancreatic and gastric cancer." (PMID 31608236, 2019).
breast carcinoma (17 papers, 2015 to 2025). "Patients with breast cancer expressing high levels of asporin are associated with a better prognosis than those with low asporin expression." (PMID 40707476, 2025). "Nevertheless, ASPN is expressed in the Hs578T breast cancer cell line, a cell line associated with a mesenchymal phenotype, and its expression can be regulated by BMP4, serum starvation, and 3D cultivation." (PMID 36358747, 2022). "The present retrospective study in breast cancer patients with 10-y follow-up underlines the importance of high asporin expression for good clinical outcome." (PMID 26327350, 2015). "Collectively, these findings strongly suggest that asporin should be considered as a future diagnostic and prognostic marker, having the potential to stratify breast cancer patients and identify those who are in need for more clinical attention." (PMID 26327350, 2015). "Besides other investigations, large scale analysis of aspartic acid repeat polymorphism will be needed for clarification of the asporin dual role in progression of breast cancer." (PMID 27409832, 2016). "However, in silico data mining on a large cohort of breast cancer patients showed that high asporin expression is associated with significantly worse RFS both in estrogen receptor positive and negative grade 3 tumors, even with metastasis to lymph nodes." (PMID 27409832, 2016). "Triple-negative breast cancer (TNBC) cells suppressed CAFs’ asporin expression by secreting IL-1β, while hormone receptor (HR) positive breast cancer induced CAFs asporin expression." (PMID 33614646, 2021). "Among the key genes, ASPN, DOCK2, THY1 and KYNU were found to be associated with breast cancer based on NCBI Entrez database." (PMID 32867782, 2020). "For example, in breast cancer, ASPN was reported as a fibroblast-derived cancer suppressor through the inhibition of TGF-β1 signaling." (PMID 30728352, 2019). "We have identified asporin as a novel breast cancer related protein by laser microdissection and microarray analysis, in particular in invasive lobular carcinomas." (PMID 27409832, 2016). "We identified asporin by microdissection and expression profiling as a novel breast cancer related protein." (PMID 27409832, 2016). "To acquire novel clues for the role of asporin in breast cancer we performed data mining using the Kaplan-Meier Plotter database comprising 4142 breast cancer patients." (PMID 27409832, 2016). "Asporin predicts good response to endocrine therapy in estrogen receptor positive breast cancer, in particular the luminal A molecular subtype." (PMID 27409832, 2016). "Andrei Turtoi and colleagues describe a mechanistic role for stroma-derived asporin in breast cancer development." (PMID 26327350, 2015). "Triple negative breast cancers appear to inhibit stromal expression of asporin at least in part via expression of the soluble signaling protein interleukin-1β." (PMID 26327350, 2015). "This gradual decrease of asporin expression with the grade of the tumor suggested a relationship between asporin expression and breast cancer progression." (PMID 26327350, 2015). "We assessed asporin protein expression retrospectively using IHC and tissues from 60 breast cancer patients with over 10-y follow-up." (PMID 26327350, 2015). "Molecular analysis of all breast cancer cell lines used in the current work suggests that only HR+ cells can induce strong asporin expression in fibroblasts." (PMID 26327350, 2015). "Invasion of breast cancer cells is dependent on ASPN and it seems to be facilitated by CAFs." (PMID 36358747, 2022). "Asporin is another tumor inhibitor protein expressed by CAFs in breast cancer." (PMID 33614646, 2021). "Asporin could enhance the proliferation, migration, and invasion capacity of pancreatic, colorectal, gastric, prostate, and breast cancer cells, indicating it could be regarded as a valuable therapeutic target." (PMID 31608236, 2019).